OPA1 (OPA1 mitochondrial dynamin like GTPase)
Diseases named in the same sentence as OPA1 in open-access papers (continued):
Sharing a sentence is not in itself a finding about the gene and the disease.
glaucoma (continued). "In addition to the identified genetic loci linked to POAG, other genetic factors e.g. OPA1, Apolipoprotein E, CYP1B1, E-cahderin, OPTC have been reported to elevate the risk of retinal degeneration characteristic of glaucoma." (PMID 20565898, 2010). "Together with the present findings, these observations indicate that reduced OPA1 may contribute to RGC pathophysiology in glaucoma." (PMID 20664796, 2010). "However, little is known about the relationship between OPA1 expression and distribution, and apoptotic cell death of RGCs in glaucoma." (PMID 19169378, 2009). "However, OPA1 variants are not linked to glaucoma in Caucasian, African American, or West African primary open-angle glaucoma (POAG) cases with elevated IOP." (PMID 39456800, 2024). "Hence, the present study was undertaken to address whether overexpression of OPA1 can protect RGCs in experimental glaucoma models, and the mechanism involved in OPA1 mediated mitochondrial fusion and parkin dependent mitophagy." (PMID 30323741, 2018). "Mitochondrial and metabolic abnormalities may put the optic nerve at risk in primary open angle glaucoma (POAG), and this preliminary study was designed to investigate whether altered OPA1 expression might be present in the progressive optic neuropathy of POAG." (PMID 21552501, 2011). "In this context, it is of particular interest that glaucomatous insults trigger OPA1 cleavage, mitochondrial fission, and mitochondrial autophagy in RGC axons of the optic nerve head in a mouse model of glaucoma." (PMID 24067127, 2013). "These similarities make OPA1, the major gene involved in ADOA, an excellent candidate gene for glaucoma, particularly NTG." (PMID 19754948, 2009). "Further, it has been hypothesized that alterations of optic atrophy type 1 (OPA1), a mitochondrial fusion protein, contribute to RGC death in glaucoma." (PMID 20664796, 2010). "In addition, we analysed genes that have been previously identified as candidate genes in glaucoma (OPTN, OPA1, CYP1B1)." (PMID 19754948, 2009). "Finally, the glaucoma inductors were able to degrade retinal tissue (p < 0.05), but VGLCR pre-treatment was able to counteract this process (p < 0.05) by overexpressing OPA1 better than the post-stimulation (p < 0.05, about 50%), confirming its protective role." (PMID 34441662, 2021). "OPA1 expression and the OPA1/β-globulin ratio were both significantly lower in primary open-angle glaucoma (POAG) patients than in controls, suggesting that decreased OPA1 expression in those patients may contribute to RGC apoptosis as one primary mechanism of optic nerve damage." (PMID 23316132, 2012). "However, the direct relationships among elevated IOP, OPA1 expression, and mitochondrial dysfunction-mediated RGC death in glaucoma remain unknown." (PMID 20664796, 2010). "Elevated IOP in glaucoma induces reduction of cytochrome c oxidase (COX) activity, mitochondrial fission, mitochondrial matrix swelling, cristae depletion, triggers release of optic nerve atrophy type-I (OPA1), and induces subsequent apoptotic cell death in differentiated RGC-5 cells." (PMID 20361014, 2010).
Ataxia (22 papers, 2010 to 2025). Ataxia refers to impaired coordination of voluntary muscle movement. "Mutations in the OPA1 gene in humans most commonly lead to ADOA with loss of vision combined with neuromuscular multisystemic dysfunctions such as ataxia and peripheral neuropathy." (PMID 39093974, 2024). "Up to 20% of patients with OPA1 disease-causing variants develop other systemic symptoms, such as sensorineural hearing loss, progressive external ophthalmoplegia, ataxia, or peripheral neuropathy, which usually follow ocular symptoms are collectively called the ADOA plus syndrome." (PMID 34573359, 2021). "OPA1 variants with a recessive inheritance mode that cause the Behr syndrome have been recently revealed in a few cases with early-onset optic atrophy, spinocerebellar degeneration, mental retardation, and developmental delay." (PMID 32883255, 2020). "Dominant optic atrophy plus (DOA+) syndrome is observed in 20% of patients with pathogenic OPA1 variants, manifesting extra-neuromuscular features like ataxia, myopathy, peripheral neuropathy, sensorineural deafness, and chronic progressive external ophthalmoplegia." (PMID 32883255, 2020). "In addition, the OPA1 mutations seem to cause a broader phenotype with ptosis, ophthalmoplegia, ataxia, axonal sensory-motor polyneuropathy, and mitochondrial myopathy." (PMID 20069065, 2010). "Recently, compound heterozygous mutations in OPA1 have been associated with Behr syndrome (OMIM#210000), a disease characterized by the association of early-onset optic atrophy with spinocerebellar degeneration." (PMID 28494813, 2017). "A proportion of OPA1 carriers will progress to a more debilitated state with variable combinations of ataxia, peripheral neuropathy, myopathy, and progressive external ophthalmoplegia in later life." (PMID 22392506, 2012). "A subset of dominant mutations in the GTPase domain of OPA1, which is directly involved in IMM fusion, has been associated with dominant optic atrophy plus syndrome, defined by the development of additional symptoms such as deafness, ataxia and myopathy throughout adulthood." (PMID 30030364, 2018). "OPA1-mutant DOA (OPA1, MIM #165500) is primarily characterized by early onset retinal ganglion cell degeneration and up to 20% of patients will also present with additional symptoms (DOA+), including deafness, ataxia, peripheral neuropathy and a worsened visual prognosis in comparison to pure DOA." (PMID 36475414, 2022).
breast carcinoma (22 papers, 2018 to 2025). "We show that OPA1 upregulation is a hallmark of metastatic breast cancer cells, which are selectively susceptible to OPA1 inhibition compared to isogenic normal or localized tumor cells." (PMID 40691145, 2025). "Elevated OPA1 levels have been observed in multiple cancers and in breast cancer they are associated with worse prognosis as well as with relapse upon chemotherapy." (PMID 40691145, 2025). "This study conducted a comprehensive analysis using multi-omics data to investigate the expression profiles of OPA1/3 in breast cancer patients and their potential diagnostic and prognostic value." (PMID 38911373, 2024). "In the case of breast cancer, several miRNAs have been identified to regulate the same biological effects caused by OPA1 deletion." (PMID 35279198, 2022). "Higher OPA1 levels were strongly associated with worse breast cancer prognosis." (PMID 35279198, 2022). "Therefore, mitochondrial dysfunction caused by OPA1 might regulate invasion and metastasis of breast cancer via the miR-148/152 family." (PMID 36647167, 2023). "In addition, researchers found that upregulation of OPA1 expression was associated with poor prognosis in breast cancer, and the research team reduced proliferation, migration, and invasion of breast cancer cells in vitro and in vivo by inhibiting OPA1 expression." (PMID 37980164, 2023). "In breast cancer, the inner mitochondrial membrane fusion protein Optic Atrophy 1 (OPA1) is upregulated and its inhibition reverses acquired chemoresistance." (PMID 40691145, 2025). "Metastatic breast cancer cells upregulate OPA1 and depend on it for respiration, migration, and proliferation." (PMID 41146909, 2025). "OPA1 levels correlate with worse breast cancer prognosis and are increased in residual TNBC following treatment with DNA-damaging chemotherapy." (PMID 40691145, 2025). "OPA1 deletion reduces tumor angiogenesis, growth, and metastasis in breast cancer, and its pharmacological inhibition restores the sensitivity to chemotherapy." (PMID 40691145, 2025). "We were surprised to observe that levels of the pro-fusion protein OPA1 were increased in the breast cancer cells displaying the most fragmented mitochondrial phenotype." (PMID 40691145, 2025). "Both clinical specimens and biobank biopsies corroborate the elevated expression of OPA1/3 in breast cancer patients." (PMID 38911373, 2024). "This comprehensive spatial transcriptomics analysis provides valuable insights into the tumor microenvironment and highlights the potential pathological significance of OPA1/3 in breast cancer." (PMID 38911373, 2024). "Overall, our pharmacogenomic analysis provides a foundation for the development of personalized therapeutic strategies targeting OPA1/3 in breast cancer patients." (PMID 38911373, 2024). "To validate the comprehensive analysis conducted, we proceeded to investigate the protein levels of OPA1/3 in breast cancer utilizing data from the Human Protein Atlas (HPA) database." (PMID 38911373, 2024). "Despite extensive scrutiny, the significance of OPA1/3 in breast cancer (BRCA) and its interplay with the immune microenvironment remain elusive." (PMID 38911373, 2024). "The findings revealed a significant increase in both transcriptional and protein levels of OPA1/3 within breast cancer tissues, showing strong correlations with various clinical parameters." (PMID 38911373, 2024). "Further research showed that OPA1 silencing inhibited breast cancer cell growth and invasion by up-regulating the expression levels of the 148/152 miRNA family while not reducing mitochondrial respiration." (PMID 37980164, 2023). "MYLS22, a first-in-class and selective inhibitor of OPA1 was shown recently to curtail breast cancer growth by inhibiting OPA1." (PMID 37900170, 2023). "In breast cancer cells with OPA1 knock-down, the expression levels of miR-148/152 family increased inhibiting tumor growth and invasion." (PMID 36647167, 2023).
breast carcinoma (continued). "By contrast, DRP1 and MFN1/2 knockout decreased stem cell differentiation in mouse embryonic cortex development and human mammary epithelial cells, respectively, and OPA1 shRNA knockdown had the same effect on human breast cancer cell lines." (PMID 38156294, 2023). "We confirmed by quantitative PCR (qPCR) the increase in miRNAs 148a, 148b and 152 levels upon OPA1 downregulation or pharmacological inhibition in all the breast cancer cell types tested." (PMID 35279198, 2022). "Silencing of OPA1 inhibited migration, proliferation and adhesion also in these other breast cancer cells." (PMID 35279198, 2022). "Our data indicate that breast cancer prognosis negatively correlates with OPA1 levels and that OPA1 genetic and pharmacological inhibition curtails breast cancer in vitro and in vivo by impinging on miRNAs of the 148/152 family." (PMID 35279198, 2022). "We identified a signature of OPA1 upregulation in breast cancer that correlates with worse prognosis." (PMID 35279198, 2022). "Because levels of the mitochondrial fusion genes MFNs were not unequivocally associated like OPA1 with worse breast cancer prognosis, we decided to concentrate our attention on the role of OPA1 in breast cancer." (PMID 35279198, 2022). "Silencing of miR-148a, miR-148b or miR-152 rescued migration, proliferation and adhesion of breast cancer cells where we had silenced OPA1." (PMID 35279198, 2022). "In summary, we demonstrate that OPA1 is highly expressed in breast cancer where its levels correlate with worse prognosis." (PMID 35279198, 2022). "Our formal epistatic analysis led to the conclusion that OPA1 ablation requires upregulation of these miRNAs to reduce breast cancer cells growth." (PMID 35279198, 2022). "We therefore performed a miRNA profiling by using miRCURY LNA Cancer Focus PCR Panel (breast cancer panel) to investigate if OPA1 deletion affected miRNAs expression." (PMID 35279198, 2022). "Surprisingly, our data identify a role for OPA1 in the regulation of the expression of miRNAs of the 148/152 family that are epistatic to OPA1 in the modulation of breast cancer hallmarks." (PMID 35279198, 2022). "The enhanced DRP1 expression and reduced OPA1 protein level is a sign of miR-195 induced increase in mitochondrial fission events in breast cancer cell lines." (PMID 30932749, 2019). "Elevated OPA1 levels correlate with poor prognosis in breast cancer and non-small cell lung cancer." (PMID 41146909, 2025). "In breast cancer, it was discovered that an upregulation of OPA1 expression could correlate with a worse prognosis and a downregulated OPA1 could attenuate its proliferation, migration and invasion." (PMID 39273403, 2024). "This study comprehensively analyzed the performance of OPA1/3 in breast cancer, including differential gene expression analysis, protein correlation analysis, pathway analysis, prognostic analysis of different tumor stages, and compared OPA1/3 expression with macrophage infiltration and immunity." (PMID 38911373, 2024). "We next wished to understand how OPA1 inhibition could influence these multiple aspects of breast cancer cell biology." (PMID 35279198, 2022). "Accordingly, OPA1 inhibition could reduce breast cancer cells proliferation, migration, and invasion in vitro and in vivo." (PMID 35279198, 2022). "Furthermore, deletion of endothelial OPA1 decreases tumor angiogenesis, growth, and metastasis in vivo models of melanoma and breast cancer, suggesting a possible role of OPA1 in the regulation of Ca2+ levels, NFκB signaling, and angiogenic gene expression." (PMID 35565283, 2022).
breast carcinoma (continued). "The effects of OPA1 ablation on breast cancer progression could therefore be OPA1 specific, or a consequence of inhibition of mitochondrial fusion per se." (PMID 35279198, 2022). "Recently, the role of OPA1 in breast cancer was systematically investigated." (PMID 36192752, 2022). "Furthermore, they revealed that miRNA 148/152 can regulate the expression of OPA1 thus affecting the migration and proliferation in breast cancer cells." (PMID 36192752, 2022). "Conversely, we posit that the effect of OPA1 on breast cancer is specific and could be mediated by its ability to control the transcription of miRNAs." (PMID 35279198, 2022). "Thus, experiments of genetic as well as pharmacological inhibition nominate OPA1 as a targetable component of breast cancer in vivo." (PMID 35279198, 2022). "Here we set out to investigate if OPA1 can be a therapeutic liability of breast cancer." (PMID 35279198, 2022). "However, it is unclear whether OPA1 is specifically upregulated in metastatic breast cancer compared to normal breast cells, questioning whether OPA1 displays a large enough therapeutic window to be safely targeted in TNBC." (PMID 40691145, 2025). "Because our bioinformatic analysis did not reveal a difference in OPA1 levels within breast cancer subtypes, we investigated whether its ablation in others breast cancer cell types caused the same phenotype observed in TNBC cells." (PMID 35279198, 2022). "Finally, we tested whether N-(1,5-dimethyl-3-oxo-2-phenyl-2,3-dihydro-1H-pyrazol-4-YL)-3-methyl-1-PH+ (MYLS22), the first in class safe and specific Opa1 inhibitor discovered in our laboratory, could recapitulate the effects of genetic OPA1 silencing on breast cancer cell phenotype." (PMID 35279198, 2022). "In summary, although OPA1 deletion induces extensive mitochondrial fragmentation in all cell lines, it is indispensable for efficient respiration only in transformed breast cancer cells, in contrast to their non-tumor isogenic counterparts." (PMID 40691145, 2025). "Thus, in metastatic breast cancer cells, active DRP1 in combination with low MFN1 levels tips the balance towards fission, whereas increased OPA1 levels tighten cristae and CJ." (PMID 40691145, 2025). "In addition, due to OPA1’s anti-apoptotic function, its targeting using MYLS22 or Opitor-0 synergizes with the BCL-2 inhibitor ABT-737 in paclitaxel-resistant breast cancer cell lines." (PMID 41146909, 2025). "We found that OPA1 mRNA was indeed upregulated in breast cancer, without any difference across different breast cancer subtypes (basal, HER2, luminal A, luminal B and normal)." (PMID 35279198, 2022). "Considering that MYC is highly expressed in some cancers, such as breast cancer and neuroblastoma, the search for inhibitors of mitochondrial fusion opens a new approach for these types of cancer as MYLS22 (OPA1 inhibitor) recently reported by Scorrano’s group." (PMID 35565283, 2022). "A study on mitochondrial transplantation in breast cancer cell lines found that the protein levels of MFN2 and OPA1 in the cells significantly increased after the transplantation of exogenous healthy mitochondria into breast cancer cells, while the protein level of drp1 dramatically decreased." (PMID 33816265, 2021). "We report that OPA1 is selectively upregulated in metastatic breast cancer irrespective of the observed fragmented mitochondrial phenotype, and that its genetic or pharmacological inhibition selectively limits proliferation and migration in metastatic over normal and transformed breast cells." (PMID 40691145, 2025). "However, our literature search found that there are currently no reports of OPA1/3 in breast cancer, so it is necessary to conduct a comprehensive analysis of OPA1/3 in breast tumors." (PMID 38911373, 2024). "Hence the down-regulation of OPA1 by miR-21 in our breast cancer lines is not consistent with this response in liver cancer." (PMID 35821197, 2022).
breast carcinoma (continued). "Our study shows that OPA1 ablation or inhibition with MYLS22, a specific, nontoxic small molecule inhibitor identified in our laboratory decreases breast cancer cell migration, proliferation, adhesion and invasion." (PMID 35279198, 2022).